ACE (angiotensin I converting enzyme)
Diseases named in the same sentence as ACE in open-access papers (continued):
Sharing a sentence is not in itself a finding about the gene and the disease.
Hypertension (continued). "Captopril (CP; 1-[(2s)-3-mercapto-2-methyl propionyl]-L- proline), an orally active inhibitor of angiotensin-converting enzyme (ACE), is in many countries the medication of choice for the management of hypertension and is often used to treat some types of congestive heart failure." (PMID 27502639, 2011). "Despite data on the association between ACE gene and MetS or hypertension are not conclusive, it appears interesting to evaluate the possible interaction of these two common polymorphisms." (PMID 22168210, 2011). "ACE inhibitors are used to treat cardiovascular and renal diseases, including hypertension." (PMID 23049672, 2011). "All patients with hypertension in the sample were on ACE inhibitors (Enalapril)." (PMID 20606950, 2010). "In our data set the M235T SNP in the AGT gene or the ID polymorphism in the ACE gene did not significantly associate with the blood pressure/hypertension phenotype." (PMID 20525211, 2010). "Moreover, angiotensin II receptor antagonists are primarily used for the treatment of hypertension when the patient is intolerant to ACE inhibitor therapy." (PMID 20717530, 2010). "Therefore, the research and development to find safer, innovative, and economical ACE inhibitors is necessary for the prevention and remedy of hypertension." (PMID 20479968, 2010). "ACE inhibitors are the agent of choice in treatment of hypertension in diabetes mellitus." (PMID 20181079, 2010). "The group of ACE inhibitors (angiotensin-converting enzyme inhibitors) is a group of pharmaceuticals (compounds such as captopril, perindopril, etc.)that are used primarily in the treatment of hypertension and congestive heart failure, and in some cases as the drugs of first choice." (PMID 20717530, 2010). "In conclusion, it can be suggested that marine-derived ACE inhibitors such as bioactive peptides, chitooligosaccharides, and phlorotannins are potential therapeutic candidates for prevent hypertension and their involvement in the future pharmaceuticals are promising." (PMID 20479968, 2010). "Hence, the aim of this review is to discuss the marine-derived ACE inhibitors and their future prospects as novel therapeutic drug candidates for treat hypertension." (PMID 20479968, 2010). "A total of 92 (19.7%) patients had hypertension diagnosed prior to breast cancer diagnosis and were therapeutically treated using a range of antihypertensives including beta-blockers, ACE inhibitors, Ca2+ antagonists, imidazoline receptor antagonists or diuretics." (PMID 21317458, 2010). "Therefore, in the development of drugs to control high blood pressure, ACE inhibition has become an important activity." (PMID 20479968, 2010). "This poor hypertension control can be improved by a more rigorous diagnostic and treatment approach, with regular use of ABPM and an increased number of prescribed antihypertensive drugs, especially of ACE inhibitors." (PMID 17955265, 2009). "The use of an ACE inhibitor was significantly associated with hypertension, but not with sex, age, diabetes, ischemic heart disease, or renal function." (PMID 19318756, 2009). "Treatment with PDE5 inhibitors in men with hypertension, including those receiving concomitant antihypertensive medications [diuretics, β-blockers and angiotensin-converting enzyme (ACE) inhibitors], has been reported to be effective and well-tolerated in managing ED." (PMID 19624789, 2009). "The present study demonstrates that ACE I/D polymorphism is not a risk factor for essential hypertension in the hitherto unstudied rural population of Haryana." (PMID 20009302, 2009). "Our study suggests that the ACE I/D polymorphism is not a risk factor for the development of essential hypertension in the studied rural population from Haryana." (PMID 20009302, 2009). "Any hypertension (> 140/90 mmHg) in a scleroderma patient should be carefully evaluated because a renal crisis is potentially reversible with appropriate management with angiotensin converting enzyme (ACE) inhibitors." (PMID 18474117, 2008).
Hypertension (continued). "Although introduced for the treatment of hypertension, angiotensin converting enzyme (ACE) inhibitors are also able to reduce morbidity and mortality in congestive heart failure and post myocardial infarction, and to prevent re-infarction, but have been found to have other benefits." (PMID 19061507, 2008). "Nevertheless, a previous study has shown a correlation between male sex and history of hypertension with serum ACE activity, which may partially support our findings." (PMID 18637188, 2008). "A review by Amenta and colleagues suggests that the treatment of essential hypertension with ACE inhibitors produces positive cognitive outcomes that are significantly better than those induced by either diuretics or beta-blockers, although all are effective in regulating hypertension." (PMID 19090988, 2008). "To look for genetic linkage between angiotensin-I converting enzyme(ACE) gene and hypertension in a Korean adolescent cohort, we developed a powerful test using the covariances between marginal differences and their variances in a transmission/non-transmission table." (PMID 17672913, 2007). "ACE inhibitors or angiotensin II receptor blockers may be of use in case of comorbity (hypertension, diabetes or left ventricular dysfunction)." (PMID 17653281, 2007). "The presence of hypertension, high levels of prothrombin time, hematocrit, hemoglobin, systolic and diastolic blood pressure, arterial pH and bicarbonate, as well as the use of ACE inhibitors, presented a negative association with death." (PMID 17262155, 2006). "Our study suggest that familial circumstances (genetic, environmental or their interaction) condition individual SBP level and seems to modify the effect of ACE inhibitors, a fact that deserves more investigation in order to improve the effectiveness of pharmacological treatment of hypertension." (PMID 16509973, 2006). "Risk assessment showed that there were no significant risk changes for hypertension in the subjects either with the ACE DD genotype (odds ratio: 1.00, 95% CI: 0.74 to 1.36, P = .98) or D allele (odds ratio: D vs. I: 1.00, 95% CI: 0.86 to 1.17, P = .98)." (PMID 15642127, 2005). "The effect of a combination of ACE and AGT gene polymorphisms on hypertension was also examined." (PMID 15642127, 2005). "Despite the limitations mentioned, this cross-sectional study does not support the notion that the ACE I/D polymorphism contributes to the prevalence and severity of essential hypertension." (PMID 15642127, 2005). "The ACE I/D polymorphism does not contribute to the presence and severity of essential hypertension, while the AGT M235T TT genotype confers a significantly decreased risk for the development of hypertension in the population studied here." (PMID 15642127, 2005). "The control of hypertension using monotherapy was more frequently attained in patients taking calcium channel blockers (80%) and beta blockers (71%), in comparison with those taking diuretics (54.9%) and ACE inhibitors (52%)." (PMID 12436155, 2002). "Fourth, the influence of treatment (e.g., inhaled corticosteroids, antifibrotic agents, ACE inhibitors/ARBs, diuretics) and comorbidities (e.g., diabetes mellitus, arterial hypertension, ischemic heart disease) may have modified the studied markers and their interrelations." (PMID 41227028, 2025). "Additionally, a study conducted in Mexico found that ACE gene polymorphisms rs4291, rs4335, rs4344, rs4353, rs4362, and rs4363 were independently associated with hypertension, independent of other hypertension-related risk factors." (PMID 40370871, 2025). "While the ACE inhibitory activity of the remaining Monascus strains was lower than that of the positive control captopril, the activity range of 16.484% to 61.538% still holds biological relevance and suggests potential utilization as a food ingredient for hypertension prevention." (PMID 40077539, 2025).
Hypertension (continued). "The ACE genotype may have a stronger association with hypertension, diabetes, and cardiovascular disease, which is not reflected when these diseases are included as comorbidities in the models." (PMID 40367215, 2025). "Anti-hypertensive (blue)—The detection of ACE-inhibitory peptides across multiple casein proteins (alpha-lactalbumin, alpha-S1-casein, and kappa-casein) reinforces the nutritional importance of these milk components in the possible modulation of hypertension and other related health issues." (PMID 40077579, 2025). "Furthermore, network pharmacology analysis revealed that IVGRPLANG and IGDEPRHQYL may interact with multiple hypertension-related targets, extending their therapeutic relevance beyond ACE inhibition." (PMID 40710492, 2025). "Additionally, the angiotensin-converting enzyme (ACE) regulates blood pressure by converting angiotensin I (Ang I) into angiotensin II (Ang II), a vasoconstrictor that narrows blood vessels and increases blood pressure, eventually leading to hypertension." (PMID 40703712, 2025). "While there are many ACE inhibitors in the market that block both domains, there are no clinically available drugs that selectively inhibit cACE (the dominant domain responsible for hypertension) or nACE (predominantly involved in fibrosis and inflammation in the heart, kidney, and lungs)." (PMID 40305366, 2025). "Therefore, bioactive peptides from marine sources can regulate hypertension by inhibiting ACE." (PMID 40278278, 2025). "Any available drug for reducing hypertension could be used, even though in patients with diabetes, angiotensin-converting enzyme (ACE) and angiotensin receptor are considered the first-line treatment for their positive effects on cardiovascular morbidity and events." (PMID 40142794, 2025). "While ACE and APOEε4 did not directly influence brain volume, modifiable risk factors like hypertension may play a crucial role in AD progression." (PMID 40372199, 2025). "Additionally, many patients with a history of hypertension in our study were likely receiving antihypertensive treatment, such as ACE inhibitors or calcium channel blockers, which are known to stabilize vascular walls by reducing inflammatory responses and oxidative stress." (PMID 40230654, 2025). "As our understanding of hypertension grew in the 1980s and 1990s, hydrochlorothiazide remained a key treatment for hypertension, even as newer drugs with fewer, if any, metabolic issues (e.g., ACE inhibitors, calcium channel blockers and β-blockers) began to replace it." (PMID 40223924, 2025). "Thus, consuming ACE inhibitors and angiotensin receptor blockers (ARBs), which are a class of drugs often used in hypertension therapy, may increase the number of ACE2 receptors, potentially increasing the binding of SARS-CoV-2 in the lungs." (PMID 40970079, 2025). "Various physio-pathological phenomena, such as ageing and hypertension, lead to a marked, time-dependent increase in ang II levels, which exacerbate both local and systemic vascular injury, accentuating the therapeutic value of ACE inhibitors and ARBs in these individuals." (PMID 40728970, 2025). "As ACE inhibitors and ARBs are used for hypertension, heart failure, and post-MI management, particularly in patients with CMD and endothelial dysfunction, investigating their synergy with LFU could provide insights into the non-invasive enhancement of both vascular and renal function." (PMID 40143180, 2025). "Additionally, in our study, important clinical variables that may affect redox biomarkers, such as diabetes, hypertension, dyslipidemia, statin or ACE inhibitor use, which may affect oxidative stress biomarkers, may be present in the disease group." (PMID 41464845, 2025). "Also, metabolites could predict a poor response to lisinopril—which is also an ACEi—in the treatment of hypertension or were related to ACE-activity." (PMID 40356784, 2025).
Hypertension (continued). "Participants who used antihypertensive medication had lower risks of newly reported fibroids: 20% lower risk compared with participants without hypertension, and 37% lower risk (for ACE inhibitors, 48% lower risk) compared with untreated participants eligible to use antihypertensive medication." (PMID 38625699, 2024). "In this sense, it should be highlighted that SARS-CoV-2 uses angiotensin-converting enzyme 2 (ACE2) as a cell receptor for viral entry, whereas ACE is the target for certain therapeutic treatments for hypertension that could prevent vasoconstriction and disease conditions in Raynaud’s phenomenon." (PMID 39599820, 2024). "A previous study summarized the pharmacogenomics of hypertension treatment, and the most common genetic variants involved in the metabolism of the five classes of drugs included ADRB1 (1165G > C), CYP2D6∗10, CYP2C9∗3, AGTR1 (1166A > C), ACE (I/D), CYP3A5∗3, and NPPA (2238T > C)." (PMID 38298191, 2024). "This coagulation dysfunction, along with the hypertension status that was observed in 58.8% of COVID-19 patients who were taking ACE inhibitors as treatment for their hypertension, could support the other findings regarding the possible association between COVID-19 infection and ICH development." (PMID 39219943, 2024). "Taken together the authors speculate that as first line treatment for hypertension in glaucoma patients thiazides and/or to a lesser extent ACE inhibitors or β-blockers, depending on concomitant comorbidities as heart failure, lung or kidney disease, could be considered (rather than CCBs)." (PMID 37995334, 2024). "In contrast, cough caused by ACE inhibitors may not be as well tolerated and may have a negative effect on quality of life in individuals with asymptomatic hypertension." (PMID 38463918, 2024). "Thus, safer and more effective natural products with ACE-inhibitory and antioxidant properties may improve the treatment of hypertension." (PMID 38933890, 2024). "The influence of ACE polymorphisms on genetic hypertension is not fully understood." (PMID 39666621, 2024). "Corn gluten meal protein hydrolysate was found to not only inhibit ACE and renin activity, but also to regulate the biosynthesis and metabolism of fatty acids, sex hormones, and aldosterone through a rat model of spontaneous hypertension, thus contributing to a reduction in hypertension." (PMID 39408244, 2024). "Since one of the primary pathophysiologies of obesity-related hypertension is through activation of the RAAS system, ACE inhibitors or angiotensin receptor blockers (ARBs) may be appropriate as an initial agent for pharmacologic therapy for hypertension in children." (PMID 39217385, 2024). "Moreover, medications including angiotensin-converting enzyme (ACE) inhibitors and angiotensin receptor blockers (ARBs) are prescribed to address hypertension, which often concomitantly exist with atherosclerosis, thus contributing to a comprehensive management strategy for the condition." (PMID 38978540, 2024). "Thus, suppressing the function of ACE proves to be a successful approach in controlling blood pressure, leading to the creation of various artificial ACE inhibitors used as medications for hypertension." (PMID 39703330, 2024). "Also, FA causes an increase in blood pressure by activating the ACE/AT1R axis, so its exposure may be involved in the development of hypertension, which has been proposed as a potential cause of the early development of CVD." (PMID 39449424, 2024). "Thus, compounds or extracts of plant origin that reduce or modulate MMPs may represent viable alternatives in the treatment of hypertension, especially when they possess vasodilatory activity through the inhibition of ACE or blocking of calcium channels." (PMID 39770106, 2024). "Therefore, the inhibition of ACE activity is a candidate treatment for the control of hypertension." (PMID 38397511, 2024).
Hypertension (continued). "Hence, a natural bioactive peptide with both DPP4 and ACE inhibitory activities may be helpful in treating or slowing down complications in diabetes and hypertension." (PMID 39595018, 2024). "Additionally, the prevalence of hypertension and the use of angiotensin‐converting enzyme inhibitors (ACE‐Is) or angiotensin II receptor blockers (ARBs) were more common, whereas the use of loop diuretics was significantly lower in the responder group than in the nonresponder group." (PMID 39101582, 2024). "However, despite the high prevalence of hypertension in the study group (64.4% of patients with carotid atherosclerosis), only 48.9% of patients took beta-blockers, 51.5% took angiotensin-converting enzyme inhibitors (ACE-inhibitors) or sartans, and 39.1% took calcium channel blockers." (PMID 37048709, 2023). "In addition to ASCVD and hypertension, ACE and ACE2 might also play a role in arthritides including RA." (PMID 37877017, 2023). "Consequently, their findings imply that ACE inhibitors, particularly ramipril, may be useful in treating hypertension individuals by lowering Hcy levels." (PMID 37886230, 2023). "In this context, some studies have demonstrated that extracts from halophyte species could be used for the prevention and treatment of heart disease and hypertension (angiotensin-converting enzyme (ACE)-inhibitory activity) due to the presence of polyphenols and bioactive compounds." (PMID 37371891, 2023). "Finally, strong ACE inhibitory activity is established for a range of karnamicins, including less substituted biosynthetic intermediates, highlighting the potential of karnamicins as drug leads for hypertension and related CVDs." (PMID 36639377, 2023). "In other regions, studies have also found that the DD genotype and the D allele were significantly associated with hypertension in Egyptian patients and Saudi patients, but ACE I/D polymorphism was not a significant factor for hypertension in the Tunisian or South Sulawesi Indonesian populations." (PMID 37091860, 2023). "Losartan is a selective antagonist of ATR1 used in the treatment of hypertension, which could also act on angiotensin II (Ang II) through a competitive mechanism upregulating the expression of the converting enzyme (ACE) or inhibiting Ang II production in situ." (PMID 37111038, 2023). "Yet, the use of ACE inhibitors as one of the standard treatments for elevated blood pressure may shed light on the role of this enzyme, specifically in monocyte/macrophages in the course of hypertension." (PMID 37854465, 2023). "Indeed, the inhibition of ACE prevents the conversion of angiotensin I to angiotensin II and, for this reason, ACE inhibitors are commonly used as pharmacological therapies for patients with hypertension." (PMID 37960264, 2023). "The conventional RAS (ACE/Ang II/AT1R) axis activation in parallel with nonconventional (ACE2/Ang 1–7/Mas) axis down-regulation was proposed to be the underlying factor leading to severe COVID-19 outcome in hypertension." (PMID 37176159, 2023). "In conclusion, hypertension and mutations in the ACE (rs4331) and ACE2 (rs2074192) genes can cause greater severity in COVID-19 patients; therefore, special attention and prompt treatment is needed in the clinical management of COVID-19 patients with hypertension." (PMID 37667339, 2023). "Therefore, the synthetic ACE inhibitory (ACEi) drugs, including captopril (Cap), lisinopril and enalapril, have been used clinically to treat hypertension, endothelial dysfunction, and diabetic nephropathy, but these ACEi drugs show serious side effects and require careful prescription management." (PMID 37502715, 2023). "Thus, novel ACE inhibitors for developing anti-hypertension drugs are needed." (PMID 37049880, 2023). "There are other sites that have been studied, such as the ACE rs4291, rs4335, and rs4363 polymorphisms, which may not be associated with hypertension but may trigger early signal metabolic changes in the hypertensive process." (PMID 37091860, 2023).